REN (renin)
Diseases named in the same sentence as REN in open-access papers (continued):
Sharing a sentence is not in itself a finding about the gene and the disease.
cardiovascular disease (continued). "Studies have shown that the activation of the renin-angiotensin system (RAS) was important for oxidative stress in many cardiovascular diseases." (PMID 35347130, 2022). "The RAS (renin–angiotensin system) plays an important role in the pathophysiology of CVD (cardiovascular disease), and RAS blockade is an important therapeutic strategy in the management of CVD." (PMID 35741131, 2022). "It is well known that as a cardiovascular disease that increases sympathetic activation, MI is characterized by sustained stimulation of β-adrenoceptors (β-ARs) and activation of the renin-angiotensin-aldosterone system." (PMID 35317286, 2022). "The beneficial effects of angiotensin-converting enzyme inhibitors, angiotensin receptor blockers, and renin inhibitors in cardiovascular diseases are well known and they seem to be augmented by targeted delivery by nanoparticles." (PMID 35456545, 2022). "Even though the activation of the renin–angiotensin–aldosterone system in the initial phases of cardiovascular diseases is compensatory, it becomes maladaptive." (PMID 35456545, 2022). "Activation of the renin-angiotensin system (RAS) is a key factor in the pathophysiology of cardiovascular disease (CVD)." (PMID 36143280, 2022). "The renin-angiotensin-aldosterone system plays a significant role in the progression of cardiovascular disease." (PMID 36110446, 2022). "Renin-angiotensin-aldosterone system hyperactivity is one of the pivotal mechanisms mediating cardiovascular diseases." (PMID 36457800, 2022). "The multifaceted nature of the renin-angiotensin system (RAS) makes it versatile due to its involvement in pathogenesis of the cardiovascular disease." (PMID 34489714, 2021). "It is reported that active metabolites of vitamin D bind to the VDR, which regulates the genes in essential processes and has a role in pathways of cardiovascular diseases, including inflammation, thrombosis, and the renin-angiotensin system." (PMID 33923622, 2021). "While the exact involvement in the pathophysiological mechanisms of renal and/or cardiovascular disease are not yet fully understood, it is known that high renin levels also have detrimental effects independent from Ang II, via binding (pro)renin receptor." (PMID 35197849, 2021). "The direct renin inhibitor aliskiren is recognized as a treatment for cardiovascular disease in diabetic patients." (PMID 33855212, 2021). "Activation of the renin–angiotensin–aldosterone system (RAAS) is considered to be an important factor that contributes to the development of cardiovascular disease in patents with CKD." (PMID 34276363, 2021). "SARS-CoV-2 is linked to the renin-angiotensin system (RAS), which plays an essential role in regulating blood pressure and the pathophysiology of cardiovascular disease." (PMID 32957997, 2020). "Pathological activation of renin-angiotensin system (RAS) is a keyfactor in several cardiovascular diseases." (PMID 31636805, 2019). "Previous studies showed that the renin-angiotensin system, particularly angiotensin II, plays an important role in various kinds of cardiovascular diseases." (PMID 31049135, 2019). "Renin-angiotensin system (RAS) is a significant contributor to development of cardiovascular diseases." (PMID 31920673, 2019). "Activation of the renin-angiotensin system (RAS) contributes to the pathogenesis of cardiovascular diseases." (PMID 31636805, 2019). "It is well known that the inhibition of the renin-angiotensin-aldosterone system reduced plasmatic levels of BNP in cardiovascular diseases." (PMID 30356256, 2018). "The majority of medications used to treat cardiovascular disease block the renin–angiotensin–aldosterone system, yet this system is activated physiologically by hypovolemia." (PMID 29751506, 2018). "Angiotensin-converting enzyme 2 (ACE2) is considered a potential therapeutic target of the renin-angiotensin system (RAS) for the treatment of cardiovascular diseases." (PMID 28445944, 2017).
cardiovascular disease (continued). "We next selected several cardiovascular disease-associated factors, including ET-1, and RAS constituents, such as renin, AGT, Ang II, AT1, and AT2, as these factors have been reported to be related to HF." (PMID 28362327, 2017). "Renin-angiotensin system (RAS) inhibitors (RASi)—widely prescribed for the treatment of cardiovascular diseases—have considerable potential in oncology." (PMID 28978752, 2017). "This has also been evoked by other authors considering the impact of sex on the renin–angiotensin–aldosterone system and its relation to cardiovascular diseases." (PMID 28230786, 2017). "The renin-angiotensin system plays a critical role in the pathophysiology of cardiovascular disease." (PMID 26846539, 2016). "The sympathetic nervous system interacts with the renin-angiotensin-aldosterone system (RAAS) contributing to cardiovascular diseases." (PMID 27661131, 2016). "Chronic activation of renin-angiotensin system is a major contributing factor to the pathogenesis and progression of cardiovascular disease." (PMID 26167285, 2015). "The renin-angiotensin system plays an important role in regulating pathophysiological processes of cardiovascular disease." (PMID 26495010, 2015). "These regions contain genes associated with calcium channels (CACNA1S), renin catalysis (REN), blood groups (ABO), apolipoprotein (APOA5), and cardiovascular diseases (RASGRP1)." (PMID 25519368, 2014). "It has been well documented that the renin–angiotensin system (RAS) plays a major role in the pathogenesis of cardiovascular diseases." (PMID 24838122, 2014). "The renin-angiotensin system is involved in multiple conditions ranging from cardiovascular disorders to cancer." (PMID 23755216, 2013). "The control group also showed a high intake of acetyl salicylic acid (ASA; 68.5 %), beta-blockers (51.9 %) and blockers of the renin–aldosterone–angiotensin system (48.1 %), suggesting the presence of cardiovascular disease." (PMID 22485015, 2012). "ACEIs (angiotensin-converting enzyme inhibitors) and ARBs (angiotensin receptor blockers) both work through the same renin-angiotensin pathway and have a similar effect in cardiovascular disease and renal protection." (PMID 22521158, 2012). "Accordingly, the pharmacological inhibition of the renin-angiotensin system improves prognosis of patients with cardiovascular disease even in settings of normal baseline blood pressure." (PMID 19390623, 2009). "Evidence from Europe, for example, has demonstrated the cost-effectiveness of polypill strategies containing aspirin, statins, and renin–angiotensin system inhibitors in patients with established cardiovascular disease, supporting its integration into guidelines and clinical pathways." (PMID 41019772, 2025). "IR can affect glucose metabolism through inflammatory factors, macrophage and adipocyte activation, and the renin–angiotensin–aldosterone system, can contribute to cardiac dysfunction and myocardial injury, ultimately leading to various cardiovascular diseases." (PMID 40405968, 2025). "The use of high-dose loop diuretics may have unfavorable prognostic implications by activating the renin-angiotensin system and sympathetic nervous system, potentially exacerbating the progression of cardiovascular diseases." (PMID 40283666, 2025). "Suppression of the renin-angiotensin-aldosterone system is therefore a key strategy in the treatment of chronic cardiovascular and renal disease and is achieved by the administration of ACEi, ARBs, and mineralocorticoid receptor antagonists, alone or in combination." (PMID 37762258, 2023). "Plasma renin was elevated in subjects with T2D and demonstrated risk factor-independent association with prevalent cardiovascular disease both in subjects with and without T2D." (PMID 27596252, 2016).
cardiovascular disease (continued). "Systemically and locally, activation of the renin-angiotensin system plays an important pathophysiological role in cardiovascular diseases, and blockade of Ang II, a key profibrotic activator of cardiac fibroblasts, has been widely shown to regress cardiac remodeling." (PMID 26327560, 2015). "First, the relationship between renin and cardiovascular disease may be obscured by the use of various drugs such as ACEIs, ARBs, beta-blockers and diuretics because these drugs modify PRA." (PMID 26167285, 2015). "Although preliminary, these results may have implications for the use of renin inhibition as a therapeutic strategy in patients with cardiovascular disease, especially in those receiving ACEI/ARB therapy." (PMID 23686372, 2013). "Since these two classes of drugs work through the same renin-angiotensin pathway and have a similar effect in cardiovascular disease and renal protection, physicians make a prescribing decision between ACEIs and ARBs when the patient needs a renin-angiotensin drugs." (PMID 22521158, 2012). "These actions could result in relevant benefits with potential clinical consequences, since activation of the renin-angiotensin system is a common feature of cardiovascular diseases." (PMID 22844495, 2012). "Our results indicated that the interactions between aspirin and renin-angiotensin-aldosterone system (RAAS) blockers required special emphasis because both are widely used in patients with cardiovascular disease, and their interactions may be overlooked in daily practice." (PMID 38646234, 2024). "The renin-angiotensin-aldosterone system (RAAS), a peptide-based system, has traditionally been viewed as a complicated linear humoral system for maintaining cardiovascular disease risk homeostasis, and it appears to play a role in the development of cardiovascular disease." (PMID 36110446, 2022). "Trend-wise, death due to cardiovascular disease has decreased and this could be the result of a higher use of disease-modifying therapy such as renin-aldosterone angiotensin system inhibitors and beta-blockers in recent years, as reported in several tertiary centres." (PMID 35342695, 2022). "In addition, IR-induced activation of the renin-angiotensin system and impaired cardiac calcium processing may also contribute to thedevelopment of cardiovascular disease." (PMID 39076642, 2022). "Furthermore, vitamin D supplementation has been suggested to be potentially preventative against cardiovascular diseases through several mechanisms including upregulation of the renin-angiotensin-aldosterone system, blood pressure increase, and ventricular musculo-hypertrophy." (PMID 36118750, 2022). "Based on the study results, it can be suggested that polyphenol fracture from bee pollen, due to a high antioxidant activity, improves endothelial functions by modulation of the renin-angiotensin-aldosterone system and may play a protective role in cardiovascular diseases." (PMID 29614743, 2018). "Use of pharmacotherapy for cardiovascular disease increased in later CKD stages, including but not limited to antithrombotics, inhibitors of the renin-angiotensin-aldosterone system, β-blockers, and calcium channel antagonists." (PMID 37180499, 2023). "As a classic and pivotal target for the treatment of cardiovascular diseases (CVD), the renin-angiotensin system (RAS) has received sustained and extensive attention." (PMID 36824459, 2023). "The renin–angiotensin system (RAS) plays a central role in the development and progression of cardiovascular disorders." (PMID 36978790, 2023). "Activation of the renin-angiotensin-aldosterone system (RAAS) is an important mechanism for the development and progression of CKD and cardiovascular disease." (PMID 34979961, 2022). "ACE2 is therefore considered an intrinsic counter-regulator of the renin-angiotensin system (RAS) and antagonizes RAS-mediated deleterious effects in not only cardiovascular disease (CVD) but also acute lung injury." (PMID 33750913, 2021).
cardiovascular disease (continued). "ACE, being a key regulator of the renin-angiotensin-aldosterone system (RAAS), is if inhibited with flavonoids, can easily manage the blood pressure and related cardiovascular disorders." (PMID 30581531, 2018). "Our findings indicated that forest bathing resulted in decreases of brain natriuretic peptide (BNP), renin-angiotensin system (RAS), inflammation, and oxidative stress, which suggested a favorable effect on cardiovascular disorders as an adjuvant therapy." (PMID 28362327, 2017). "Prolonged oxytocin administration did not affect plasma concentrations of renin and atrial natriuretic peptide, but was associated with the activation of calcium-dependent protein phosphatase calcineurin, a canonical signalling mechanism in pressure overload-induced cardiovascular disease." (PMID 26393919, 2015). "Furthermore, activation of beta-1 adrenergic receptors encourages the secretion of renin, which enhances the activity of the renin-angiotensin system (RAS), a significant contributor to the development of various cardiovascular diseases." (PMID 37746367, 2023). "Furthermore, dogs fed for 60 days with an herbal source of choline (800 mg/kg of diet) showed a reduction in the expression of genes involved in the renin-angiotensin system and PPAR, which are related to the prevention of cardiovascular diseases." (PMID 36230399, 2022). "The impact of genes of the renin-angiotensin and kinin-bradykinin systems in the development of cardiovascular disease in athletes has not been defined." (PMID 36140844, 2022). "The renin–angiotensin system and the AT1 receptor are the targets of several classes of therapeutics (such as angiotensin converting enzyme inhibitors or angiotensin receptor blockers, ARBs) used as first-line treatments in cardiovascular diseases." (PMID 34201646, 2021). "Renin-angiotensin system (RAS) plays an important role in the pathogenesis of cardiovascular diseases, and intervention of the RAS plays beneficial effects in cardiovascular diseases." (PMID 32509148, 2020). "Furthermore, there are no specific recommendations or guidelines for treating cardiovascular disease in females compared to males, including cardiovascular therapies with recognized sex differences such as those targeting the renin–angiotensin system." (PMID 39064064, 2024).
kidney disease (219 papers, 2009 to 2026). "The ameliorative effects of taurine against renal disorders are based on its osmoregulatory properties, its association with signaling pathways and its association with the renin-angiotensin-aldosterone system (RAAS)." (PMID 36699147, 2021). "Renin not only has vital functions in cardiovascular and kidney disease, but also is associated with diverse cancers, especially BC." (PMID 34228637, 2021). "Previous studies have demonstrated that acquired factors associated with various kidney diseases, including oxidative stress, ischemia, and renin–angiotensin–aldosterone system activation, can lead to mitochondrial injury." (PMID 31877839, 2019). "Inhibition of the renin–angiotensin system reduces the risk of kidney disease progression and treatments that lower blood pressure (BP) or low-density lipoprotein cholesterol reduce cardiovascular (CV) risk in this population." (PMID 30524708, 2018). "We report a novel dominant REN mutation discovered in an individual after forty years of renal disease." (PMID 28701203, 2017). "From the mid-1990s, considerable studies on genetic polymorphism of the renin-angiotensin have been done as part of effective agents in prediction of renal diseases." (PMID 26311652, 2015). "Early detection of kidney disease in patients with diabetes is important because close monitoring of cardiovascular risk factors, and specific drugs acting on the renin-angiotensin system slow down the progression of renal disease." (PMID 22905926, 2012). "Several studies had shown a relationship between genetic variants of the renin-angiotensin system genes and renal diseases as well as the rate of progression of renal damage." (PMID 21859496, 2011). "Furthermore, ADRA1A affects renal functions via regulating Na+ reabsorption, renin secretion, renal blood flow and glomerular filtration rate, of which alterations cause kidney disease." (PMID 36134646, 2023). "Adiposity may be a potential risk factor for the development of kidney disease due to upregulated renal plasma flow, intraglomerular pressure, and renin-angiotensin-aldosterone system activity." (PMID 35330131, 2022). "CIH, a key characteristic of OSA, might result in renal disease via its potential association with inflammation, increased sympathetic nervous system activity, activation of the renin–angiotensin–aldosterone system, intrarenal hypoxia, and oxidative stress." (PMID 36386819, 2022). "Renin (REN) mutations are involved in REN-related kidney disease and tubular dysgenesis." (PMID 33959146, 2021). "Combination therapies of amlodipine with other agents causing blockade of the renin–angiotensin–aldosterone pathway (angiotensin II receptor blockers or renin inhibitors) have shown successful blood pressure reduction approaches to decrease the risk of CV and progression of renal disease." (PMID 34553070, 2021). "Along the same line of thinking, we believe that renal disease caused by the L381P mutant could be alleviated by using chemical chaperones that may rescue mutant renin trafficking along the secretory pathway." (PMID 31406136, 2019). "In this case report, we describe a novel dominant REN mutation discovered as part of a transplant work up and aim to highlight the importance of investigating a genetic diagnosis in patients with long-standing renal disease and a relevant family history." (PMID 28701203, 2017). "An alteration in the activity of the renin–angiotensin–aldosterone system could be another pathological mechanism of the risk of kidney disease." (PMID 26466096, 2015). "A major hypothesis in the nephrology literature is that proteinuria (albuminuria) underlines the progression of diverse forms of kidney disease and that the renoprotective effects of inhibitors of the renin–angiotensin system are partly mediated through their antiproteinuric effect." (PMID 28664159, 2017).